RPL17P35 (ribosomal protein L17 pseudogene 35)
Synonyms: RPL17_9_1049
Gene: Processed pseudogene on chromosome 10 (64,620,374 to 64,620,922, reverse strand). Ensembl gene ENSG00000233900.
Diseases named in the same sentence as RPL17P35 in open-access papers:
RPL17P35 is named in the same sentence as 1 disease in open-access papers, as found by Europe PMC text mining. Sharing a sentence is not in itself a finding about the gene and the disease.
RPL17P35 shares sentences with these, for which no sentence is quoted: opioid dependence (1 paper).